FOXC2 (forkhead box C2)
Diseases named in the same sentence as FOXC2 in open-access papers (continued):
Sharing a sentence is not in itself a finding about the gene and the disease.
esophageal cancer (7 papers, 2012 to 2022). A primary or metastatic malignant neoplasm involving the esophagus. "In colorectal and esophageal cancer, FOXC2 expression correlated with poor prognosis and the loss of FOXC2 function decreased the invasive and migratory abilities of cancer cells in vitro." (PMID 27634875, 2016). "We previously reported the significance of FOXC2 expression in patients with esophageal cancer and cholangiocarcinoma, and a high expression of FOXC2 in tumor tissues was found to be related to cancer progression and a poor prognosis." (PMID 29801468, 2018). "FoxC2 is also expressed by tumor cells in human breast, colonic, and esophageal cancer and participates in the epithelial-mesenchymal transition (EMT), a key process that leads to the invasion and metastasis of aggressive tumors." (PMID 22174714, 2012). "Additionally, FOXC2 expression in esophageal cancer cell lines facilitated vascular tube formation by human umbilical vascular endothelial cells (HUVEC)." (PMID 36230774, 2022). "Moreover, we previously reported that FOXC2 suppression by RNA interference induces anti-proliferative activity in esophageal cancer cells and cholangiocarcinoma cells." (PMID 29801468, 2018). "FOXC2 expression has also been reported in esophageal cancer and could be used as a novel independent prognosis factor." (PMID 24647631, 2014). "In addition, co-amplification of FOXC2 and FA2H was observed in 185 patients with esophageal cancer from TCGA cohort, whereas no prominent correlation was found between FA2H and the other three TFs." (PMID 36274060, 2022).
diabetes (6 papers, 2011 to 2025). "Our previous study found a link between the C-512T polymorphism of the FOXC2 gene and glucose-lipid metabolism abnormalities in diabetes." (PMID 41404514, 2025). "Notably, recent studies have found that FOXC2 also affects diabetes by regulating intestinal epithelial function." (PMID 41404514, 2025).
glioblastoma (6 papers, 2022 to 2024). The most malignant astrocytic tumor (WHO grade IV). "CircKIF18A from glioblastoma-associated microglia can bind to FOXC2 in human brain microvessel endothelial cells (hBMECs), and maintain the stability and nuclear translocation of FOXC2." (PMID 37759870, 2023). "FOXC2 is a transcription activator contributing to gene overexpression in various cancers, like glioblastoma." (PMID 38978133, 2024). "CircKIF18A can bind to the transcription factor FOXC2 to promote angiogenesis in glioblastoma by activating the PI3K/AKT signaling pathway." (PMID 38379858, 2024). "Exosomal circKIF18A promotes angiogenesis by targeting FOXC2 in glioblastoma (GBM)." (PMID 37122733, 2023). "Downregulation of FOXC2 was present only in the glioblastoma cell line." (PMID 36142793, 2022).
melanoma (6 papers, 2012 to 2024). A malignant, usually aggressive tumor composed of atypical, neoplastic melanocytes. "In that study, we also described a novel CRISPR-Cas9 gene-edited variant of the murine B16-F1 melanoma that we engineered to lack the FOXC2 transcription factor (B16-F1ΔFOXC2)." (PMID 32175283, 2020). "In a B16 mouse melanoma model, Foxc2 deficiency reduced tumor growth and neovascularization and was associated with impairments in mural-cell coverage and increases in endothelial-cell apoptosis in tumor blood vessels." (PMID 22174714, 2012). "The RNA-seq data discussed in this article have been made publicly available in NCBI's Gene Expression Omnibus under Dataset Name “RNA-seq Analysis of Differential Gene Expression in Wild-type Versus FOXC2-deficient B16-F1 Melanomas” (GEO Series accession number GSE134296)." (PMID 32175283, 2020). "Importantly, these data reveal a role for FOXC2 in the regulation of multiple pathways with oncogenic potential in melanoma, and they offer mechanistic insights into FOXC2-associated tumor progression that may be applicable to other cancer types as well." (PMID 32175283, 2020). "Using this model, we demonstrated a role for FOXC2 in promoting melanoma progression, and we highlighted select data from an RNA-seq analysis of the B16-F1 and B16-F1ΔFOXC2 melanomas that we now describe here in more detail." (PMID 32175283, 2020). "We recently reported that expression of the FOXC2 gene in melanoma biopsies is an unfavorable prognostic indicator of patient survival following treatment with either chemotherapy or immunotherapy." (PMID 32175283, 2020). "While previous studies have focused on FOXC2 in the context of cancers originating from epithelial tissues, we recently demonstrated that FOXC2 is also a key contributor to the progression of melanoma." (PMID 32175283, 2020). "Homozygous mutations of FoxC2 lead to perinatal lethality, so the role of FoxC2 in melanoma was confirmed by subcutaneously implanting mouse B16 melanoma cells in wild-type and heterozygous FoxC2 mutant (FoxC2+/–) mice." (PMID 22174714, 2012). "FoxC2 expression has been detected in the tumor endothelium of both human and mouse melanomas, which suggests that FoxC2 has a role in tumor angiogenesis." (PMID 22174714, 2012). "Indeed, our recent analysis of melanoma patient TCGA data showed that FOXC2 expression correlates negatively with progression-free survival (PFS) of patients treated with the CTLA-4 immune checkpoint inhibitor ipilimumab." (PMID 32175283, 2020). "In order to gain additional insights into FOXC2 activity in human melanoma, we are also in the process of evaluating by immunohistochemistry how FOXC2 expression levels in melanoma patient biopsies correlate with expression of proteins of interest that have emerged from this study." (PMID 32175283, 2020). "In this regard, that our B16-F1ΔFOXC2 model represents to our knowledge the first complete FOXC2 knockout cell line underscores the potential utility of this system for gaining important mechanistic insights into a potentially alternate driver of melanoma progression." (PMID 32175283, 2020). "Other genes involved in oncogenesis bore melanoma-specific ZEB1 binding sites which were either lost in MDA-MB-231 cells, such as for the WNT regulators TLE4 (Groucho) SFRP1 or FOXC2." (PMID 38519642, 2024). "For example, in a melanoma xenograft model, mice lacking one copy of Foxc2 exhibited reduced tumor growth, impaired formation of tumor blood vessels, and decreased pericyte coverage." (PMID 36230774, 2022).
triple-negative breast carcinoma (6 papers, 2017 to 2022). An invasive breast carcinoma which is negative for expression of estrogen receptor (ER), progesterone receptor (PR), and human epidermal growth factor receptor 2 (HER2). "In this study, we show that SNAI2, a mediator of EMT highly expressed in triple-negative breast cancer, is upregulated in endocrine-resistant cells, whereas other EMT-associated transcription factors, such as SNAI1/3, TWIST1/2, ZEB1/2, FOXC2, and GSC, are unaltered." (PMID 29921289, 2018).
non-small cell lung carcinoma (5 papers, 2016 to 2022). A group of at least three distinct histological types of lung cancer, including non-small cell squamous cell carcinoma, adenocarcinoma, and large cell carcinoma. "The purpose of this study is to assess the prognostic value of FoxC2 expression in non-small cell lung cancer (NSCLC), alone or in combination with E-cadherin expression." (PMID 26758745, 2016). "Forkhead box protein C2 (FOXC2) was shown to promote resistance to the same drug by induction of EMT in non-small cell lung cancer A549 cells by activating v-akt murine thymoma viral oncogene homolog 1/ Glycogen synthase kinase 3 (AKT/GSK3) signaling pathway and increased expression of Snail." (PMID 34003341, 2021).
pancreatic cancer (5 papers, 2018 to 2022). "The true prevalence of FOXC2 mutations in pancreatic cancer remains to be established." (PMID 35720978, 2022). "In contrast, lncRNA CF129 (CF129145.1) was confirmed to inhibit the invasion and metastasis of pancreatic cancer cells by interfering with the transcription of FOXC2 (forkhead box protein C2)." (PMID 33520725, 2020). "To further assess the regulation of CF129 on FOXC2 expression, we measured FOXC2 mRNA level in the same cohort of the 40 pancreatic cancer tissues." (PMID 31367258, 2019). "Kaplan-Meier and log-rank test analyses showed that pancreatic cancer patients with high FOXC2 expression had a shorter overall survival time than those patients with low FOXC2 expression." (PMID 31367258, 2019). "Furthermore, a significant inverse correlation was observed between CF129 and FOXC2 transcript levels in 40 pancreatic cancer specimens (r=-0.723, p<0.039)." (PMID 31367258, 2019). "Therefore, the present study demonstrates a lncRNA-interacted feedback of HIF-1α and FOXC2 which is involved in pancreatic cancer progression during hypoxia microenvironment." (PMID 31367258, 2019). "Thus, we presumed that FOXC2 might be a relevant CF129 target in pancreatic cancer." (PMID 31367258, 2019). "Moreover, the publicly available databases for pancreatic cancer (GEO profiles, GDS4102) also displayed that FOXC2 was significantly higher in human PC tissues than that of NP tissues." (PMID 31367258, 2019).
heart failure (4 papers, 2022 to 2025). Inability of the heart to pump blood at an adequate rate to meet tissue metabolic requirements. "For example, notable genes such as FOXC2 and NOTCH3, identified in familial VV, are also implicated as shared factors in the pathogenesis of heart failure." (PMID 39775444, 2025). "In keep with our hiPSC-CM observations, telomere signal negatively correlated with FOXC1 and FOXC2 protein expressions in human heart failure biopsies." (PMID 38634789, 2024). "Moreover, FOXC1 and FOXC2 protein levels correlated positively in heart failure biopsies." (PMID 38634789, 2024). "In a mouse model of heart failure, blocking VEGF-C/VEGFR-3-mediated signals (AKT/ERK1/2, calcineurin A/NFATc1/FOXc2 and CX43) resulted in decreased cardiac lymphangiogenesis and increased cardiac dysfunction." (PMID 36064450, 2022).
liver cancer (4 papers, 2020 to 2024). An epithelial or non-epithelial malignant neoplasm that arises from the liver. "In conclusion, the BHB-Glow medium was able to hinder the expression of FOXC2 by hindering insulin production, thereby suppressing the proliferation and migration of liver cancer cells." (PMID 39344752, 2024). "Specifically, it was a metabolic regulation at the systemic level, in which the BHB-Glow medium hindered FOXC2 expression by interfering with glycolytic metabolism and inhibiting insulin production, thereby inhibiting liver cancer cells’ malignant progression." (PMID 39344752, 2024). "In liver cancer, KD hindered the expression of FOXC2 by reducing insulin production, thereby repressing the proliferation and migration of liver cancer cells in vitro." (PMID 39344752, 2024). "We found significant up-regulation of FOXC2 in liver cancer tissues by bioinformatics analysis, and high expression of FOXC2 in liver cancer cells by qPCR." (PMID 39344752, 2024). "Together, the medium simulating KD environment strengthened the protection of liver cancer cells by reducing insulin production and down-regulating FOXC2 expression." (PMID 39344752, 2024). "Dual-luciferase reporter assays showed that PART1 can sponge miR-3529-3p, which targets FOXC2 in liver cancer cells." (PMID 34484336, 2021). "Overall, these data suggested that the downregulation of PART1 can inhibit the proliferation and differentiation of Hep3B cells by targeting the hsa-miR-3529-3p/FOXC2 axis and thus hinder the occurrence and development of liver cancer." (PMID 34484336, 2021). "Expression of FOXC2 in liver cancer cells was analyzed by bioinformatics and qPCR." (PMID 39344752, 2024). "Together, FOXC2 was considerably up-regulated in liver cancer and could foster liver cancer cells to migrate and proliferate." (PMID 39344752, 2024). "Therefore, we hypothesized that simulating a KD in vitro may lead to a decrease in insulin production and downregulation of FOXC2 expression in liver cancer cells, thereby inhibiting liver cancer cell proliferation and migration." (PMID 39344752, 2024). "This study confirmed through in vitro cell experiments that KD could inhibit the proliferation and migration of liver cancer cells by targeting down regulation of insulin and FOXC2 expression, providing new theoretical basis for the treatment of liver cancer patients." (PMID 39344752, 2024). "However, determining whether FOXC2 participates in the liver cancer development and mediates the Akt signalling pathway as a target gene of miR-3529-3p requires further investigation." (PMID 34484336, 2021). "Therefore, the present study aimed to investigate the potential role of lncRNA PART1 and its expression pattern in regulating the occurrence and development of liver cancer through miR-3529-3p by targeting the FOXC2-mediated Akt signalling pathway in Hep3B cells." (PMID 34484336, 2021). "Hence, liver cancer can be inhibited by suppressing lncRNA PART1 and miR-3529-3p expression on the basis of the blocking effect of FOXC2 and AKT protein expression." (PMID 34484336, 2021).
Varicose veins (4 papers, 2014 to 2024). Enlarged and tortuous veins. "It has been shown in different studies that the FOXC2 gene shows differences in gene expression in blood and vascular tissues, and that some variants create a predisposition to varicose veins." (PMID 39858587, 2024). "The FOXC2 gene was the first to be linked with the etiology of varicose veins, playing a key role in development and function of venous valves." (PMID 31921319, 2019). "Yet there have been no further studies on FoxC2 genetic variants in patients with varicose veins." (PMID 24608096, 2014). "The role of FoxC2 gene however has not yet been well-defined in patients with varicose veins or CVD." (PMID 24608096, 2014).
Axenfeld-Rieger syndrome (3 papers, 2013 to 2023). Axenfeld-Rieger syndrome (ARS) is a generic term used to designate overlapping genetic disorders, in which the major physical condition is anterior segment dysgenesis of the eye. "Interestingly, mutations within PITX2, which physically interacts with FOXC1 and FOXC2, have previously been linked to the ocular conditions Axenfeld-Rieger syndrome and glaucoma." (PMID 36868229, 2023). "Among them, Foxc1 and Foxc2 have attracted the most attention in view of their association with Axenfeld-Rieger syndrome (ARS)." (PMID 23533700, 2013).
colitis (3 papers, 2023 to 2025). Inflammation of the colon. "There is also some evidence that Foxc2 haploinsufficiency in mice increases their susceptibility to DDS‐induced colitis; however, the precise function of FOXC1 and FOXC2 in vascular repair and intestinal regeneration after ischemic injury have yet to be determined." (PMID 37154714, 2023).
colon cancer (3 papers, 2014 to 2020). "High FOXC2 expression is strongly correlated with invasion and metastasis of CRC, whereas downregulation of FOXC2 reduces colon cancer invasiveness and their metastatic potential." (PMID 32372224, 2020). "Genistein reversed the EMT of colon cancer cells by upregulation of E-cadherin and downregulation of N-cadherin, accompanied by the suppression of EMT related makers, such as Snail2/slug, ZEB1, ZEB2, FOXC1, FOXC2 and TWIST1." (PMID 29202800, 2017).
esophageal squamous cell carcinoma (3 papers, 2020 to 2025). Esophageal squamous cell carcinoma (ESCC) is a type of esophageal carcinoma (EC) that can affect any part of the esophagus, but is usually located in the upper or middle third. "In a murine study, miR-4707-3p was found to interact with DANCR to regulate the expression of FOXC2 oncogene, in a zinc finger protein 750 (ZNF750) dependent manner, which affected esophageal squamous cell carcinoma angiogenesis." (PMID 41039543, 2025).
glaucoma (3 papers, 2019 to 2023). Increased pressure in the eyeball due to obstruction of the outflow of aqueous humor. "We also evaluated the possible modifier role of FOXC2 and PITX2 defects on patients with CYP1B1 glaucoma-associated genetic backgrounds." (PMID 30657791, 2019). "To investigate possible oligogenic inheritance involving FOXC2 or PITX2 and CYP1B1, we also analyzed FOXC2 and PITX2 variants in a group of 25 CG cases who were known to carry CYP1B1 glaucoma-associated genotypes." (PMID 30657791, 2019). "Given the relevance of TM biomechanics in glaucoma development and the observation of elevated IOP in NC-Foxc2-/- mice, further studies focused on the role of Foxc2 on TM biomechanics are warranted." (PMID 37414529, 2023).
hypoplastic left heart syndrome (3 papers, 2009 to 2023). Hypoplastic left heart syndrome (HLHS) refers to the abnormal development of the left-sided cardiac structures, resulting in obstruction to blood flow from the left ventricular outflow tract. "In contrast to the association of point mutations in FOXF1 with bowel malrotation, microdeletions of FOXF1 were associated with hypoplastic left heart syndrome and gastrointestinal atresias, probably due to haploinsufficiency for the neighboring FOXC2 and FOXL1 genes." (PMID 19500772, 2009). "The Endo_EC gene cluster had nine genes, including Notch1 and Foxc2 (Fig. 6Bii), which expressed at all stages and were preferentially related to Hypoplastic Left Heart Syndrome (HLHS), Bicuspid Aortic Aalve (BAV), and Tetralogy of Fallot (TOF)." (PMID 36575170, 2022).
Insulin resistance (3 papers, 2016 to 2022). Increased resistance towards insulin, that is, diminished effectiveness of insulin in reducing blood glucose levels. "FOXC2 inhibits adipogenic differentiation in vitro and transgenic mice with adipocyte-specific FOXC2 overexpression exhibit a lean phenotype and are protected against diet-induced insulin resistance." (PMID 36230774, 2022). "Also, overexpression of Foxc2 in HFD-fed mice was associated with reduced fat mass and complete protection from diet-induced insulin resistance, intramuscular accumulation of lipid, and hepatic insulin resistance." (PMID 28105413, 2016).
invasive breast carcinoma (3 papers, 2014 to 2025). A carcinoma that infiltrates the breast parenchyma. "We then performed an EMTome correlative study examining the expression of WNT/β-catenin and FOXC2 across invasive breast carcinoma subtypes." (PMID 40227590, 2025). "To investigate the clinical significance of the upstream (PLK1) and downstream (CDK1) modulators of FOXC2, we analyzed the data from a cohort of patients with invasive breast cancers following taxane-anthracycline chemotherapy." (PMID 27064522, 2016). "FOXC2 was later confirmed to be upregulated in invasive breast cancers and some other metastatic cancers of patients." (PMID 25216525, 2014). "Moreover, the significance of this observation is reiterated by our finding that PLK1 and the FOXC2 potential target CDK1 mRNA collectively predict poor DRFS among invasive breast cancer patients after taxane-anthracycline chemotherapy." (PMID 27064522, 2016).
lung adenocarcinoma (3 papers, 2014 to 2021). A carcinoma that arises from the lung and is characterized by the presence of malignant glandular epithelial cells. "One finding of our study is the starkly inverse association between FoxC2 and E-cadherin expression in both lung adenocarcinoma and squamous cell carcinoma." (PMID 26758745, 2016). "We found that FoxC2 expression was heterogeneously present in lung adenocarcinoma and squamous cell carcinoma." (PMID 26758745, 2016). "In a study involving CLI-5 and A549 lung adenocarcinoma cells, resveratrol downregulated miR-520h and triggered miR-520h-mediated signal cascade, resulting in inhibition of forkhead box C2 (FOXC2) and subsequent suppression of tumour metastasis in both in vitro and in vivo models." (PMID 25254214, 2014).